RNASE4 (ribonuclease A family member 4)
Diseases named in the same sentence as RNASE4 in open-access papers:
RNASE4 is named in the same sentence as 31 diseases in open-access papers, as found by Europe PMC text mining. Sharing a sentence is not in itself a finding about the gene and the disease. The quoted sentences say what the papers report.
amyotrophic lateral sclerosis (2 papers, 2018 to 2019). Amyotrophic lateral sclerosis (ALS) is a neurodegenerative disease characterized by progressive muscular paralysis reflecting degeneration of motor neurons in the primary motor cortex, corticospinal tracts, brainstem and spinal cord. "Similarly, a single nucleotide polymorphism in the RNASE4 gene has been shown to affect its ribonuclease activity leading to the development of amyotrophic lateral sclerosis (ALS)." (PMID 30463297, 2018). "Importantly, polymorphisms, and recently, pathogenic mutations have associated RNase 4 with Amyotrophic Lateral Sclerosis (ALS) development." (PMID 31849926, 2019).
colitis (2 papers, 2024 to 2025). Inflammation of the colon. "The exacerbation of colitis observed in Rnase4-deficient mice, as well as the association between Rnase4 and gut microbiota dysbiosis, imply possible clinical potential of RNASE4 in IBD management, including Ulcerative colitis (UC) and Crohn’s disease (CD)." (PMID 38987259, 2024). "The amelioration of disease symptoms was accompanied by a significant reduction in the level of Parasutterella, implying that reversion of dysbiosis underlies the therapeutic efficacy of Rnase4 in experimental colitis, at least partially." (PMID 38987259, 2024). "Importantly, Rnase4ΔIEC mice also developed severe colitis upon DSS treatment, reinforcing the role of intestinal epithelial cell-derived Rnase4 in modulating colitis susceptibility." (PMID 38987259, 2024). "The exacerbated colitis observed in WT (co-Rnase4−/−) mice could potentially be attributed to alterations in their gut microbiota composition, resulting from the ingestion of fecal matter from their Rnase4-deficient cage mates." (PMID 38987259, 2024). "The strong link between dysbiosis and intestinal inflammation prompted us to investigate the effect of Rnase4 on mouse colitis." (PMID 38987259, 2024). "WT mice were cohoused with either age- and sex-matched Rnase4−/− mice (WT (co-Rnase4−/−)) or with WT littermates (WT (co-WT)) born from heterozygous Rnase4+/− parents for a period of 6 weeks prior to the induction of colitis." (PMID 38987259, 2024). "The results revealed that WT (co-Rnase4−/−) mice exhibited an exacerbated inflammatory response compared to their non-cohoused WT counterparts or WT (co-WT) controls, as evidenced by colitis indicators." (PMID 38987259, 2024). "To confirm the existence of the “Rnase4–Parasutterella–tryptophan metabolism–colitis” regulatory axis, we implemented a rescue experiment wherein Rnase4−/− mice were orally administered with KYNA and XANA during DSS administration." (PMID 38987259, 2024). "Overall, our results demonstrated that Rnase4-regulated Parasutterella downregulated KYNA and XANA metabolism in intestinal epithelial cells, thereby enhancing intestinal susceptibility to colitis." (PMID 38987259, 2024). "To identify the specific colitis-related microbes, we tried to isolate and culture the top enriched bacteria from Rnase4−/− mice, and only successfully obtained a Parasutterella strain." (PMID 38987259, 2024). "The WT recipients that received fecal transplants from Rnase4−/− donors displayed aggravated colitis symptoms relative to those receiving feces from WT donors." (PMID 38987259, 2024). "To further explore how Parasutterella affects colitis, we analyzed the metabolites in stool samples from WT and Rnase4−/− mice." (PMID 38987259, 2024). "Interestingly, oral administration of the recombinant mouse RNase 4 in RNASE4−/− mice successfully ameliorates the symptoms of colitis and reduces Parasutterella population." (PMID 41230022, 2025). "Specifically, studies in mice revealed that RNase 4 modulates the intestinal microbiome by selectively limiting Parasutterella growth while promoting the indoleamine‐2,3‐dioxygenase 1 (IDO1) pathway and reducing colitis risk." (PMID 41230022, 2025). "To investigate whether Rnase4 suppresses colitis by modulating gut microorganisms, we designed a microbiota manipulation experiment." (PMID 38987259, 2024). "Importantly, we observe a decreased level of RNASE4 and increased abundance of Parasutterella in IBD patient samples, and demonstrate that exogenous Rnase4 supplementation can restore the gut microbiome composition and attenuate the severity of colitis." (PMID 38987259, 2024). "We further elucidate the antibacterial mechanism of this protein on Parasutterella, and establish a host-microbiota interaction pathway—i.e., intestinally secreted Rnase4–gut Parasutterella–epithelium tryptophan metabolism–gut microbiota—that contributes to the pathogenesis of colitis." (PMID 38987259, 2024).
colitis (continued). "Interestingly, upon DSS administration, WT mice gavaged with the Parasutterella strain suffered from more severe colitis, confirming the role of Rnase4-regulated bacteria in colitis." (PMID 38987259, 2024). "In this study, we observed decreased RNASE4 levels, increased Parasutterella abundance, and downregulated tryptophan metabolism in both the experimental colitis model and patients with IBD, suggesting that these factors might serve as IBD diagnostic biomarkers." (PMID 38987259, 2024). "Notably, mice pretreated with Rnase4 exhibited attenuated signs of colitis." (PMID 38987259, 2024). "We demonstrate that Rnase4 acts as an antimicrobial protein, modulating the gut microbiota composition by specifically targeting and killing Parasutterella, thereby enhancing the production of kynurenic and xanthurenic acid through the IDO1 pathway and ultimately reducing colitis susceptibility." (PMID 38987259, 2024). "To investigate the therapeutic potential of Rnase4, we orally treated Rnase4−/− mice with the recombinant Rnase4 protein for 30 days, followed by DSS administration to induce colitis." (PMID 38987259, 2024). "To validate this hypothesis, we performed a fecal microbiota transplantation, where age- and sex-matched WT or Rnase4−/− donor feces were orally gavaged into the gastrointestinal tract of antibiotic-pretreated WT recipient mice every other day for a period of 2 weeks before DSS-induced colitis." (PMID 38987259, 2024). "To confirm our observations, we examined the effect of Rnase4 in another colitis model—i.e., an acute 2,4,6-trinitrobenzene sulfonic acid solution (TNBS)-induced colitis model—and obtained similar results." (PMID 38987259, 2024).
diabetes (2 papers, 2022 to 2025). "Additional evidence for the importance of RNase 4 in host defence of the urinary tract has been generated in the context of diabetes mellitus (DM), a prevalent human condition associated with increased UTI susceptibility." (PMID 41230022, 2025). "Since diabetes is known to compromise several antimicrobial peptides like hBD-1, RNase4, RNase7, and LCN2, our results are of special relevance and suggest a mode to reestablish the expression of antimicrobial peptides in type 2 diabetes patients." (PMID 34651203, 2022).
bacterial urinary tract infection (1 paper, 2025). A bacterial infectious process affecting any part of the urinary tract, most commonly the bladder and the urethra. "Both human and mouse RNase 4 demonstrate potent activity at low micromolar concentrations against uropathogenic E. coli (UPEC), which is the leading cause of bacterial urinary tract infections (UTIs) in humans." (PMID 41230022, 2025).
heart failure (1 paper, 2017). Inability of the heart to pump blood at an adequate rate to meet tissue metabolic requirements. "Previous studies showed RNASE4 to be associated with high-altitude adaptation, metabolic syndrome and neuron degeneration, while JDP2 was associated with heart failure." (PMID 28423658, 2017).
irritable bowel syndrome (1 paper, 2024). Irritable bowel syndrome (IBS) is a chronic functional condition of the lower gastrointestinal (GI) tract characterized by abdominal pain or discomfort and disordered bowel habit (diarrhea, constipation, or fluctuation between the two). "Among the Rnase4-targeting bacteria, Parasutterella has been reported to be associated with various health outcomes, including CD, irritable bowel syndrome, obesity, and type 2 diabetes." (PMID 38987259, 2024).
liver cancer (1 paper, 2021). An epithelial or non-epithelial malignant neoplasm that arises from the liver. "Immunohistochemistry was also performed in 10 paired of liver cancer and adjacent tissues to furthermore measure the expression of RNASE4 and GRHL2." (PMID 34235075, 2021). "Furthermore, we performed RT-qPCR assays, which confirmed the expression of RNASE4 and GRHL2 in 30 pairs of liver cancer and adjacent tissues." (PMID 34235075, 2021).
melanoma (1 paper, 2019). A malignant, usually aggressive tumor composed of atypical, neoplastic melanocytes. "In this study, CYR61, DUSP1, and RNASE4 were identified as potential genes of interest for future molecular studies in melanoma, which would improve our understanding of its causes and underlying molecular events." (PMID 30925905, 2019).
neuropathic pain (1 paper, 2026). Chronic pain caused by damage to nerve fibers. "Moreover, in a neuropathic pain model, RNase4 expression was upregulated in nociceptors during the pain and recovery phases, and its deletion altered mechanical sensation." (PMID 41876491, 2026).
prostate carcinoma (1 paper, 2022). A carcinoma that arises from epithelial cells of the prostate gland. "In this study, we demonstrate that RNASE4 is up-regulated in prostate cancer, and has diagnostic, prognostic and therapeutic values." (PMID 35752711, 2022). "RNASE4 represents as a new diagnostic biomarker for prostate cancer and can distinguish cancer from BPH." (PMID 35752711, 2022). "Besides the prognostic and diagnostic value of RNASE4 in prostate cancer, this study also demonstrated a functional role of RNASE4 in promoting prostate cancer progression by stimulating cancer cell proliferation and probably also by promoting angiogenesis." (PMID 35752711, 2022). "RNASE4 protein in prostate cancer tissues is enhanced and can differentiate prostate cancer and BPH." (PMID 35752711, 2022). "Taken together, these results provide in vivo evidence that RNASE4 is a therapeutic target for the treatment of prostate cancers." (PMID 35752711, 2022). "RNASE4 protein level in the plasma is elevated in prostate cancer patients and is positively correlated with disease stage, grade, and Gleason score." (PMID 35752711, 2022). "We next examined the cell-autonomous function of RNASE4 in prostate cancer proliferation by knocking down RNASE4 in PC-3, DU145, and LNCaP cells using two RNASE4-specific shRNAs (shRNASE4-1 and shRNASE4-2) with a non-targeting shRNA control (shControl)." (PMID 35752711, 2022). "RNASE4 stimulates prostate cancer cell proliferation, induces tumor angiogenesis, and activates receptor tyrosine kinase AXL as well as AKT and S6K." (PMID 35752711, 2022). "A RNASE4-specific mAb has been shown to inhibit prostate cancer cell growth in vitro, in soft agar, and in athymic mice." (PMID 35752711, 2022). "ROC curve analysis of ANG showed an AUC of 0.79 at the 394 ng/ml optimal cut-off value, confirming that it is a good diagnosis marker for prostate cancer, but RNASE4 was better with a higher AUC value (0.94)." (PMID 35752711, 2022). "In The Cancer Genome Atlas (TCGA) prostate dataset, RNASE4 DNA copy number was also higher (p = 1.94 × 10−7) in prostate cancer tissues (n = 171) than in healthy tissues (n = 61)." (PMID 35752711, 2022). "To explore the prognostic value of RNASE4, we examined the correlation between RNASE4 expression and prostate cancer aggressiveness." (PMID 35752711, 2022). "Immunoblot and qRT-PCR analyses showed that RNASE4 expression is higher in prostate cancer cell lines PC-3, DU145, and LNCaP than in normal prostate epithelial cell line RWPE-1." (PMID 35752711, 2022). "To investigate the functional role of RNASE4 in prostate cancer, we examined the effects of exogenous RNASE4 on prostate cancer cells, and found that RNASE4 stimulates proliferation of DU145 and PC-3 cells." (PMID 35752711, 2022). "IHC analysis of RNASE4 in prostate cancer TMA revealed that the tissue level of RNASE4 was also positively correlated with histopathological characteristics of prostate cancer patients." (PMID 35752711, 2022). "To evaluate the therapeutic value of targeting RNASE4 in prostate cancer therapy, we examined the effect of human RNASE4-specific mAb on prostate cancer cell proliferation." (PMID 35752711, 2022). "We report that RNASE4 expression is increased progressively in prostate cancer, correlates with aggressiveness of the disease, can accurately distinguish between healthy, BPH, and prostate cancer, and can independently predict biopsy outcome." (PMID 35752711, 2022). "We also demonstrate that RNASE4 inhibition decreases prostate cancer growth in vitro and in vivo, underscoring a therapeutic potential of RNASE4 inhibitors in prostate cancer treatment." (PMID 35752711, 2022). "It is notable that the plasma level of RNASE4 protein has the potential to serve as an accurate blood biomarker for prostate cancer to predict disease aggressiveness." (PMID 35752711, 2022).
prostate carcinoma (continued). "RNASE4 level in the plasma samples of healthy control subjects (n = 120) and prostate cancer patients (n = 120) were determined by an in-house prepared ELISA." (PMID 35752711, 2022). "Knockdown of RNASE4 decreased cell proliferation and reduced both the number and the size of prostate cancer cell colonies in soft agar." (PMID 35752711, 2022). "RNase 4 is presented as a biomarker for prostate cancer, inducing AXL activation that promotes AKT/S6K activation and tumor cell proliferation, and its inhibition reduces the growth of xenograft human prostate tumors." (PMID 35752711, 2022). "The main finding of this study is that RNASE4, a ribonuclease previously unknown to have any involvement in prostate cancer, was found to play a role in prognosis, diagnosis, and treatment of prostate cancer." (PMID 35752711, 2022). "Consistent with a role of AXL in RNASE4-induced prostate cancer growth, we found that RNASE4 knockdown or treatment with RNASE4 mAb in xenograft animal models resulted in a reduction of AXL phosphorylation without affecting the total AXL levels in the tumor tissues." (PMID 35752711, 2022). "Thus, RNASE4 level in prostate cancer tissues was higher than in BPH (p = 0.0006) and normal prostate tissue (p = 0.0005)." (PMID 35752711, 2022). "In silico analysis of RNASE4 mRNA utilizing Oncomine human multi-cancer datasets also revealed an up-regulation of RNASE4 mRNA in various types of human cancers, with the highest up-regulation observed in prostate cancer." (PMID 35752711, 2022). "Another notable finding of this study is that RNASE4 may serve as a therapeutic target for drug development in the treatment of prostate cancer." (PMID 35752711, 2022). "Our study shows that RNASE4 is a new serum and tissue biomarker for prostate cancer." (PMID 35752711, 2022). "In addition, we uncovered a previously unknown mechanism of action in which RNASE4 mediates prostate cancer cell proliferation and tumor growth by activating AXL receptor tyrosine kinase and downstream effectors AKT and S6." (PMID 35752711, 2022). "RNASE4-specific mAb may thus have an impact in prostate cancer diagnosis and treatment." (PMID 35752711, 2022).
sarcoma (1 paper, 2022). A usually aggressive malignant neoplasm of the soft tissue or bone. "Upregulated mtRBP genes included Fus (fused in sarcoma), Puf (pumillo and FBF 60 homolog), Rexo2 (RNA exonuclease 2), and RNasel and RNase4 (ribonucleases)." (PMID 35754828, 2022).
squamous carcinoma (1 paper, 2017). "In subtype squamous carcinoma CC patients, minor allele “C” of rs512715 in NEAT1 and minor allele “C” of rs3094 in RNASE4 were associated with increased risk." (PMID 28423658, 2017).
infection (4 papers, 2019 to 2025). The state of being infected such as from the introduction of a foreign agent such as serum, vaccine, antigenic substance or organism. "Similarly to RNase 4, RNase 7 is secreted by bladder urothelium and the kidney’s ICs to prevent colonisation and infection caused by bacterial pathogens." (PMID 41230022, 2025). "While some of these peptides, including RNase 4 and RNase 7, are abundantly produced by epithelial cells, the expression of others, like RNase 3 and RNase 6, increase at infection sites with immune cell recruitment." (PMID 31849967, 2019). "Moreover, RNases, such as RNASE4, are acutely induced during infection and downregulated during prolonged infection periods." (PMID 38193073, 2023). "However, at this moment the lack of loss of function experiments with RNase 4 KO mice currently prevents us from accurately understanding the true importance of this protein in the protection of the urinary tract against infections." (PMID 41230022, 2025).
tumor (3 papers, 2005 to 2022). "Most importantly, RNASE4 is associated with diseases of higher Gleason, higher biopsy grade, higher tumor stage, and higher risk of metastasis, and may thus serve as a prognosis marker." (PMID 35752711, 2022). "Our results also demonstrate a correlation between the plasma RNASE4 level and tumor grade, stage, metastasis and prognosis." (PMID 35752711, 2022). "The effect of RNASE4 knockdown on tumor growth was examined in a xenograft animal model with PC-3 cells." (PMID 35752711, 2022). "The anti-tumor activity of RNASE4 mAb was first examined in a prophylactic setting in a xenograft animal model in which PC-3 cells were inoculated into athymic mice and treatment was started the next day." (PMID 35752711, 2022). "Now we show that RNASE4 mAbs inhibited RNASE4-induced angiogenesis in vitro and decreased neovessel density in the tumor tissue." (PMID 35752711, 2022). "Similarly we have little knowledge of what functions that RNase A family, 4 (RNASE4) plays in the tumor growth." (PMID 17407572, 2007). "The other six genes with more than two-fold upregulation in more than five tumours arrayed were CCNG2 in 30 tumours, NDRG1 in 18 tumours, PFKFB3 in 17 tumours, RNAse4 in 10 tumours, Adrenomedullin (ADM) in eight tumours and Glucose transporter 1 (GLUT-1) in six tumours." (PMID 16052224, 2005). "The tumor-bearing animals were separated into 3 groups according to tumor sizes so that each group had animals with matched tumor sizes, and treated with PBS (n = 12) or with RNASE4 mAb at 10 mg/kg (n = 6) or 30 mg/kg (n = 6), respectively, by i.p. injection once every 3 days for 39 days." (PMID 35752711, 2022).
cancer (2 papers, 2016 to 2022). A tumor composed of atypical neoplastic, often pleomorphic cells that invade other tissues. "Indeed, univariate and multivariate regression analyses confirmed the significance of RNASE4 as a predictive biomarker of cancer outcome either used alone or together with PSA." (PMID 35752711, 2022). "Thus, plasma RNASE4 level can provide valuable information on cancer aggressiveness and can predict biopsy outcome, and may stratify patients for the need of biopsy." (PMID 35752711, 2022). "Three isoforms GP2, RNASE4 and ADRA2A amongst top down-regulated genes are not reported to be differentially expressed in cancer." (PMID 28330331, 2016).
RNASE4 also shares sentences with these, for which no sentence is quoted: arterial hypertension (2 papers); asthma (1); Cirrhosis (1); connective tissue disorder (1); Crohn disease (1); fibrosis (1); herpesvirus infections (1); hypertension (1); inflammatory bowel disease (1); metabolic syndrome (1); metastatic prostate carcinoma (1); Obesity (1); prostate tumors (1); skin tumors (1); type 2 diabetes (1); ulcerative colitis (1).